IL33 (interleukin 33)
Diseases named in the same sentence as IL33 in open-access papers (continued):
Sharing a sentence is not in itself a finding about the gene and the disease.
Sepsis (continued). "Some studies indicate that IL‐33 could play a role in immunosuppression during the later stages of sepsis, potentially linked to Treg proliferation and activation, as well as the release of Th2‐type cytokines." (PMID 40453734, 2025). "Genetic deficiency of either IL-33 or ST2 prevented ILC2p egression from BM following sepsis." (PMID 35272622, 2022). "However, the elevated level of IL‐33 can also cause immune suppression via expansion of Tregs, which is commonly observed in sepsis‐surviving patients." (PMID 32566227, 2020). "IL-33 is protective during acute phase of sepsis, keratitis caused by Pseudomonas aeruginosa or Staphylococcus aureus wound infection and in parasitic diseases with Trichuris muris, Schistosoma mansoni, or Toxoplasma gondii, whereas it is deleterious during cutaneous and visceral leishmaniasis." (PMID 29867945, 2018). "In addition, it has been reported that exogenous IL-33 exhibits immunoprotective role in polymicrobial sepsis in mice by preventing early loss of T and B lymphocytes." (PMID 30001716, 2018). "In this study, we show that IL-33 increases in response to the systemic inflammation and tissue damage caused by experimental septic peritonitis, remaining elevated in the lung tissue for days after recovery from sepsis." (PMID 28374774, 2017). "Thus, the polymorphism could be mechanistically linked to sepsis survival by the IL-33 concentration and could represent a novel biomarker for sepsis." (PMID 38338680, 2024). "However, in the late phase of uncontrolled sepsis, the downside of the sustainable enhanced neutrophil recruitment mediated by IL-33 may cause secondary remote organ damage in the late phase of sepsis." (PMID 39991638, 2024). "In addition, sepsis, a severe systemic infectious disease, also resulted in increased IL-33 level in the thymus, and as a consequence, caused thymic involution in mice and humans, while IL-33 deficient mice displayed the normal morphology, weight, and cellularity of the thymus during sepsis." (PMID 36371464, 2022). "Here, we demonstrate that IL-33 results in immunosuppression by inducing thymic involution-associated naive T cell dysfunction with aberrant expression of aging-associated genes and impairs host control of infection in mouse disease models of schistosomiasis or sepsis." (PMID 36371464, 2022). "In the context of severe sepsis and septic shock, the excessive release of IL-1, IL-18, and IL-33 leads to cytokine storm characterized by uncontrolled inflammation and widespread tissue damage." (PMID 41300951, 2025). "IL‐33 can increase macrophage pyroptosis in mice with sepsis by activating the NF‐kB/p38MAPK signaling pathway." (PMID 40849678, 2025). "Monitoring changes in IL-33 is valuable for predicting outcomes and distinguishing sepsis from systemic inflammatory response syndrome (SIRS)." (PMID 41300951, 2025). "Studies investigating the therapeutic potential of targeting the IL-33/ST2 axis in sepsis have shown mixed results." (PMID 40406124, 2025). "It has been theorized that IL-33 has both beneficial and detrimental effects in sepsis depending on the time course and micro-environment." (PMID 40406124, 2025). "In childhood sepsis, there is a significant increase in serum IL-33 levels observed from the first day of sepsis compared to control samples." (PMID 40406124, 2025). "During early sepsis, IL-33 plays an important anti-inflammatory role, enhances neutrophil migration and bacterial clearance, decreases lymphocyte apoptosis and suppresses Th17 responses, which improves early survival." (PMID 40076848, 2025). "Targeting the IL-33/ST2 axis, implicated in enhancing TIGIT+ Treg suppressive function during late sepsis, represents another potential strategy." (PMID 40806563, 2025). "It is also reported that IL-33 treatment suppressed pro-inflammatory cytokines production and improved the survival rate in sepsis mice by suppressing the IL-17 pathway through activating the suppressor of cytokine signaling (SOCS)-3." (PMID 39991638, 2024).
Sepsis (continued). "There is increasing evidence that suggests that IL-33 is involved in the initiation and progression of inflammatory diseases, such as sepsis." (PMID 39991638, 2024). "There are significantly higher levels of IL-33 or sST2 in blood in the early phase of childhood sepsis." (PMID 39991638, 2024). "Due to its biological characteristics, IL-33 can act as a double-edged sword in sepsis: It not only contributes to clear bacteria and improves survival but also causes inflammation, immunosuppression, and organ damage via modulating immune response." (PMID 39991638, 2024). "Taken together, these findings suggest that IL-33 plays an essential dual-functional role in the progression of sepsis, the role of IL-33 in sepsis appears to be time and concentration-dependent." (PMID 39991638, 2024). "In this review, we provide recent advances in IL-33-mediated immune regulation and its effect on sepsis." (PMID 39991638, 2024). "Understanding the intrinsic link between IL-33, mechanical ventilation, and sepsis is fundamentally important for the development of rational strategies for the treatment of different stages of sepsis and the prevention of its associated complications." (PMID 39991638, 2024). "In this review, we will summarize updated information on the dual functions of IL-33 in the host immune response to sepsis." (PMID 39991638, 2024). "As a result of tissue damage in sepsis, IL-33 is released, promoting an immunosuppressive response due to the excessive stimulation of anti-inflammatory mediators." (PMID 39199173, 2024). "High levels of IL-33 have been found in survivors of sepsis, which in part contributes to a state of persistent immune paralysis." (PMID 38558800, 2024). "A study showed that the TIGIT+ Treg subset expanded via IL-33/ST2/STAT6/M2 macrophages in the immunosuppressive state of sepsis." (PMID 38082335, 2023). "IL-33 treatment played a protective activity against sepsis and also significantly reduced mortality in CLP septic mice." (PMID 38114466, 2023). "During sepsis, IL-33 released by damaged cells initiates a signaling cascade through its receptor ST2 on M2 macrophages that favors the expansion of the highly suppressive TIGIT+FOXP3+T regulatory cells." (PMID 37604833, 2023). "IL-33 is released from tissue injury during sepsis and activates type 2 innate lymphocytes, which promote the polarization of M2 macrophages, enhancing the expansion of Treg cell populations via IL-10." (PMID 38082335, 2023). "By inducing the expansion of IL-10 secreting M2 macrophages, and promoting the accumulation of regulatory T cells (Tregs), IL-33 has been proposed as a potential mediator of long-term immunosuppression in murine models of sepsis." (PMID 37662933, 2023). "An earlier study also reported an increased abundance of serum IL-33 upon the diagnosis of sepsis, which decreased on the 3rd and 7th day of antibiotic treatment." (PMID 36769133, 2023). "Our results were opposite to the results of other studies because they suggested that IL-33 values were decreased in patients who died from sepsis in comparison to patients who survived." (PMID 38152329, 2023). "The role of IL-33 in sepsis is becoming increasingly prominent, and understanding its significance in the treatment of sepsis associated with high mortality is critical." (PMID 38082335, 2023). "In sepsis, the induced production of IL-33 represents a trade-off between acute protection and distant immunosuppression." (PMID 37153553, 2023). "During the immunosuppressive phase of sepsis, IL-33 levels increased and remained high for five months after recovery." (PMID 38114466, 2023). "IL-33 is released in sepsis to activate neutrophils and prevent bacterial growth while repairing tissue, but high IL-33 levels can lead to immunosuppression." (PMID 37153553, 2023). "In a mouse model of sepsis, administration of IL-33 treatment improved inflammation and reduced mortality." (PMID 36294336, 2022).
Sepsis (continued). "Sepsis patients showed an increase in a few of the pro-inflammatory cytokines i.e., IL-6, IL-8, IL-18, IL-33, IP-10, MIF, MIP1a, MIP1β, and MIP3a, along with the growth factors i.e., LEPTIN, GCSF, MCSF and ESelectin." (PMID 35681439, 2022). "sesamin improves the 7-day survival rate of septic mice, suppresses the inflammatory response in sepsis through the HMGB-1/TLR4/IL-33 signaling pathway." (PMID 35720285, 2022). "We used a mouse sepsis model induced by CLP to show that sepsis initiates ILC2p egress from BM in an IL-33/ST2 signaling-dependent manner." (PMID 35272622, 2022). "Collectively, these results indicate that IL-33/ST2 signaling promotes ILC2 egress from BM following sepsis." (PMID 35272622, 2022). "To elucidate the role of IL-33 in mediating ILC2 mobilization following sepsis, we measured IL-33 protein concentrations in the blood up to 24 h after CLP." (PMID 35272622, 2022). "Taken together, reduced IL-33 production in aging mice impaired ILC2p mobilization from BM in sepsis." (PMID 35272622, 2022). "In the patients with detectable IL‐33 levels, those in the sepsis group showed a significantly higher circulating IL‐33 level than those in the control group." (PMID 35593197, 2022). "Sepsis was induced by cecal ligation and puncture (CLP) model in wild-type, IL-33-deficient and ST2-deficient mice." (PMID 35272622, 2022). "Collectively, we reported low PANX1 expression in donor grafts prior to LT and decreased IL‐33 levels after LT in clinical patients with sepsis." (PMID 35593197, 2022). "Here, by using mouse disease models of schistosomiasis and sepsis, we demonstrated that IL-33-mediated thymic involution resulted in naive T cell dysfunction with aberrant expression of aging-associated genes and impaired host control of severe infection." (PMID 36371464, 2022). "In this study, we show that systemic IL-33 levels increase in response to sepsis, and increased IL-33 is required for ILC2p egress from BM and expansion in the lung." (PMID 35272622, 2022). "To determine the role for IL-33 in mediating sepsis-induced ILC2 egression, we intraperitoneally injected WT mice with recombinant mouse soluble ST2 (sST2), the soluble form of IL-33 receptor, at 30 min prior to CLP." (PMID 35272622, 2022). "IL-33 exerts protective effects in experimental sepsis-induction with cecal ligation and puncture (CLP), and while its protective mechanism is TH2-independent, it acts through enhancing the migration of neutrophils into the infected sites to clear bacteria." (PMID 34638904, 2021). "After modeling of sepsis in IL-33-/- transgenic mice, theactivation of the NF-κB/p38 MAPK signaling pathway was significantly inhibited; thepyroptosis of macrophages was suppressed; and the septic mice mortality rate wasreduced." (PMID 34133503, 2021). "Clinically, anti-sepsis targeted therapeutic effects of IL-38 is amplified when combined with IL-5, IL-7, IL-30, and IL-33." (PMID 34830435, 2021). "CXCR1 and CXCR2 in human neutrophils are well established receptors for the neutrophil chemoattractant, IL-8, and others have shown modulated CXCL1 and chemokine receptor expression by IL-33 in bacterial infections and sepsis in animal models." (PMID 34266437, 2021). "IL-33 controls neutrophil recruitment during sepsis by preventing downregulation of CXCR2 and inhibition of chemotaxis induced by the activation of TLR4 in mouse and human neutrophils." (PMID 33673387, 2021). "IL-33 can increase the level of macrophage pyroptosis in mice with sepsis (byactivating the NF-kB/p38MAPK signal pathway) and the mortality of thesemice." (PMID 34133503, 2021). "This IL-33 dependent ALI during sepsis also occurs via IL-5 upregulation in pulmonary ILC2s, and the IL-5 neutralization decreases the neutrophil infiltration, and ALI during sepsis." (PMID 32849610, 2020).
Sepsis (continued). "IL-33 contributes significantly to sepsis-induced inflammation in the lung, early inflammation-associated lung injury, and systemic inflammatory response in the early phase of sepsis by upregulating the level of ILC2s." (PMID 33178840, 2020). "A study in CLP-induced sepsis has shown the increase in ILC2s in the peritoneum and small intestine along with the increased IL-13 and IL-33 levels in the peritoneal lavage fluid (PLF) within 24 h post sepsis development." (PMID 32849610, 2020). "The findings were consistent between the in vitro and in vivo models; both pre- and post-transcriptional levels of HMGB1, TLR4, and IL-33 were significantly downregulated in the sesamin-treated sepsis group." (PMID 32893702, 2020). "This review focuses on recent advances in the understanding of the regulation and function of ILC2s in sepsis-induced lung inflammation; in particular, the balance between IL-33/ST2 and PD-L1/PD-1 signaling in ILC2s." (PMID 33053762, 2020). "On the one hand, IL‐33 attenuates polymicrobial‐induced sepsis in mice by accelerating microbial clearance and neutrophil recruitment." (PMID 32566227, 2020). "Sesamin improved the 7-day survival rate of septic mice, suppressed the inflammatory response in sepsis through the HMGB-1/TLR4/IL-33 signalling pathway, and further alleviated intestinal injury." (PMID 32893702, 2020). "This evidence suggests that sesamin can suppress the HMGB1/TLR-4/IL-33 signalling pathway, the activation of which is possibly involved in the in vitro LPS-induced sepsis model." (PMID 32893702, 2020). "In the current study, a septicemic mouse model was established by infecting mice with S. epidermidis (ATCC 12228) in order to analyze the effects of IL-33 on the development of septicemia and the production of PGE2, IL-17A, and IL-22." (PMID 33178181, 2020). "Recent work on the cytokines IL-17, IL-27, and IL-33 suggest the presence of a novel cytokine axis during sepsis." (PMID 31507598, 2019). "IL-33 signaling has been shown to improve sepsis survival in the short term in murine models, although one report suggests that IL-33 is linked to the development of immunosuppression during sepsis." (PMID 31507598, 2019). "Recent evidence links interleukin (IL)-17, IL-27, and IL-33 to alterations in the immune response during sepsis using patient serum and murine models of peritonitis and pneumonia." (PMID 31507598, 2019). "In contrast, IL-33 levels increase in patient serum during the immunosuppressive stage of sepsis and remain high for more than 5 months after recovery." (PMID 31507598, 2019). "This review will describe how IL-17, IL-27, and IL-33 exert these effects during sepsis and their potential as therapeutic targets." (PMID 31507598, 2019). "For example, IL-33 has been shown to attenuate sepsis by enhancing neutrophil influx to the site of infection in the lethal CLP model." (PMID 30944018, 2019). "While IL-33 attenuates sepsis mortality, it is less clear if this is due to any effect on the Th17 response." (PMID 31507598, 2019). "Murine models have demonstrated IL-33 can protect from sepsis and enhance antimicrobial neutrophil chemotaxis and also anti-inflammatory regulatory T cells and ILC2s62–66." (PMID 31221971, 2019). "Conversely, a protective role of IL-33 was observed in atherosclerosis, sepsis, allograft transplant and parasite infection." (PMID 30863362, 2019). "In the sublethal CLP model followed by Legionella pneumophila infection, IL-33 also contributed to sepsis-induced long-term immunosuppression by expanding the regulatory T cell population." (PMID 30944018, 2019). "Using a cecal ligation and puncture (CLP) mouse sepsis model, we demonstrated that IL-33, which is released in response to sepsis, acting through its receptor ST2 mediates ILC2 expansion in the lungs." (PMID 29511181, 2018).
Sepsis (continued). "We demonstrate here that IL-33, which is released mainly by epithelial cells in response to sepsis, acting through its receptor ST2 induces ILC2 expansion in the lungs." (PMID 29511181, 2018). "Collectively, these results strongly indicate a role for IL-33/ST2 signaling in ILC2 expansion in the lungs following sepsis." (PMID 29511181, 2018). "The elevated level of soluble ST2 in patients with polymicrobial sepsis indicated the important role of IL-33/ST2 axis in sepsis pathogenesis." (PMID 30001716, 2018). "It was previously reported that IL-33 attenuates sepsis by promoting neutrophil infiltration as well as improving bacterial clearance in the peritoneal cavity." (PMID 30001716, 2018). "To determine a causal relationship between the decreased ILC2 in the lungs and increased MLEC death in Il-33−/− mice following sepsis, we co-cultured ILC2 with mouse MLEC in vitro in the presence and absence of LPS and TNFα, which mimic sepsis stimulation." (PMID 29511181, 2018). "Our data, therefore, uncover a function of IL-33 in sepsis-induced immunosuppression and identify a target for potential treatment of this adverse long-term outcome induced by sepsis." (PMID 28374774, 2017). "In this review, we will discuss the current understanding of the role of IL-33 and its regulatory targets in the host response during sepsis." (PMID 28168040, 2017). "Collectively, these results indicate that type 2 cytokines mediate the development of sepsis-induced immunosuppression, an effect regulated by IL-33/ST2 signalling." (PMID 28374774, 2017). "We then addressed the contribution of type 2 cytokines and IL-33 on M2 polarization of macrophages in sepsis-surviving mice." (PMID 28374774, 2017). "Our study raises the possibility of targeting IL-33 to ameliorate sepsis-induced long-term immunosuppression following recovery from infection." (PMID 28374774, 2017). "IL-33, released during tissue injury in sepsis, activates type 2 innate lymphoid cells, which promote polarization of M2 macrophages, thereby enhancing expansion of the Treg cell population via IL-10." (PMID 28374774, 2017). "Since IL-33 can expand Treg cell population and these cells have been shown to mediate sepsis-induced immunosuppression, we next investigated the potential function of IL-33 in the induction of Treg cells in CLP-induced immune dysfunction." (PMID 28374774, 2017). "In this review, we provide an update on recent advances on IL-33-mediated immunoregulation in sepsis." (PMID 28168040, 2017). "Data presented here show that IL-33/ST2 signalling leads to a significant expansion of Foxp3+ Treg cell population expressing ST2 in sepsis-surviving mice." (PMID 28374774, 2017). "In summary, our results have identified a previously unrecognized dual role of IL-33 in sepsis survivors." (PMID 28374774, 2017). "Here the authors show expansion of the Treg cell population in sepsis mice is driven by IL-33-induced ILC2 activation of IL-10 production by macrophages." (PMID 28374774, 2017). "IL-33, released during the widespread tissue injury, induces ILC2s expansion and M2 polarization of macrophages in sepsis survivors, promoting a wound healing process." (PMID 28374774, 2017). "In contrast, the production of IL-10 in the lungs of Il1rl1−/− and Stat6−/− mice was markedly reduced at day 15 after CLP, suggesting that type 2 cytokines and IL-33 are involved in the production of IL-10 in sepsis-surviving mice." (PMID 28374774, 2017). "Mice deficient in ST2 (IL-33R) develop attenuated immunosuppression in cases that survive sepsis, whereas treatment of naive wild-type mice with IL-33 induces immunosuppression." (PMID 28374774, 2017). "In this review, we focus on the recent advances in understanding the role of the IL-33/ST2 axis in sepsis." (PMID 28168040, 2017). "Sepsis-surviving patients had significantly higher concentrations of IL-33 and IL-10 in their serum and more circulating Treg cells compared to those of the healthy controls." (PMID 28374774, 2017).